ALB (albumin)
Diseases named in the same sentence as ALB in open-access papers (continued):
Sharing a sentence is not in itself a finding about the gene and the disease.
chronic kidney disease (continued). "Chronic kidney disease is defined as Estimated glomerular filtration rate <90 mL/min/1.73 m2 or albumin-to-creatinine ratio ≥ 3mg/mmol." (PMID 36325265, 2022). "It is known that both high- and low-serum bicarbonate levels have been associated with an increased risk of mortality and serum bicarbonate were inversely related to serum albumin and phosphate levels in patients with end stage renal disease." (PMID 35793495, 2022). "DKD was diagnosed with impaired glomerular filtration rate (< 60 mL/min/1.73 m2 assessed by using the Chronic Kidney Disease Epidemiology Collaboration algorithm), albuminuria (urine albumin to creatinine ratio ≥ 30 mg/g), or both in T2DM patients." (PMID 36561561, 2022). "On the basis of eGFR and urine albumin measurements, chronic kidney disease is classified into six stages of eGFR (G1, 2, 3A, 3B, 4, and 5) and three proteinuria stages (A1, 2, and 3)." (PMID 35268426, 2022). "Elevated urinary albumin–creatinine ratio and early stages of chronic kidney disease were parameters widely used to inform treatment decisions, even if thresholds for urine protein level and for glomerular filtration rate differed." (PMID 35135579, 2022). "In patients with chronic kidney disease, urinary albumin-creatinine ratio was measured in 27% of patients and only 55% had chronic kidney disease documented in their health record." (PMID 34401719, 2021). "Logistic regression analysis indicated that chronic kidney disease (OR = 14.0), CRP >100 IU/L (OR = 6.964), and S. albumin <3 gm/dl (OR = 8.0) were risk factors associated with mortality and can guide in risk stratification." (PMID 34285680, 2021). "In this context, serum albumin concentration has also been shown to be an independent marker in predicting mortality in patients with end-stage renal disease (ESRD)." (PMID 34984121, 2021). "The inverse relationship between serum albumin levels and survival has been established in many other clinical circumstances, such as end-stage renal disease and preoperative context." (PMID 34367693, 2021). "During these different periods, it is recommended to assess the nutritional status of chronic kidney disease patients by regular monitoring of weight, biological values (albumin), appetite and food consumption." (PMID 34371943, 2021). "Taken together, 16 days of HSD-feeding in OZR was associated with renal hyperfiltration, a response that can be maladaptive over time in the progression of chronic kidney disease (CKD) and one that is typically associated with a progressive increase in albumin excretion rate." (PMID 35197849, 2021). "Similar to liver diseases, serum ALB redox has been investigated well in the context of chronic kidney diseases (CKDs)." (PMID 33804859, 2021). "Chronic kidney disease, low albumin, hypovolemic shock, and insurance type were predictors of AF risk unique to this model." (PMID 33812369, 2021). "In contrast, the increase in TGF-β1 levels due to chronic renal failure was positively correlated with the urinary albumin level." (PMID 34940691, 2021). "It is shown that fibrinogen can be used as a predictor of end-stage renal disease in type 2 diabetes, and plasma albumin can be used as an indicator of the prognosis of renal disease." (PMID 34098959, 2021). "It has been shown that a higher CRP/ALB ratio is an independent prognostic factor in conditions as diverse as chronic kidney disease, lung cancer and severe sepsis." (PMID 33779823, 2021). "A recent cohort study involving 3430 patients with chronic renal insufficiency also found that increased levels of TNF-α and decreased serum albumin in patients with chronic renal disease were associated with rapid loss of renal function." (PMID 34992536, 2021). "Plasma-oxidized albumin levels correlate with a decrease in estimated glomerular filtration rate and an increase in blood urea nitrogen in patients with chronic kidney disease." (PMID 33800425, 2021).
chronic kidney disease (continued). "The UV absorbance at 215 nm involves an interference with the separation of HMA and HNA-1 by uric acid, which is a critical obstacle especially for the determination of serum ALB redox state in chronic kidney disease (CKD) patients." (PMID 33804859, 2021). "Neonatal complications occurred in the offspring of 3 mothers who had end-stage renal disease (ESRD) caused by primary glomerulonephritis and serum albumin levels (sAlb) ≤ 3.2 mg/dL in the first trimester." (PMID 34591251, 2021). "Compared with adrenocortical hormones or immunosuppressants, TGt can significantly reduce 24-hour urinary protein, increase plasma albumin, and improve the cure rate in patients with chronic kidney disease." (PMID 34093720, 2021). "Renal disease included chronic kidney disease, which is defined as a decrease in glomerular filtration rate and increase in albumin excretion." (PMID 34349179, 2021). "Elevated urinary albumin-to-creatinine ratio is a measure of kidney damage, and used to diagnose and stage chronic kidney disease." (PMID 34887417, 2021). "Urine albumin and creatinine, which are commonly used biomarkers of chronic kidney disease (CKD), were used to demonstrate the effectiveness of the proposed GWT-GMR sensor in practical biosensing applications." (PMID 33430392, 2021). "Colloidal osmotic pressure was increased by ALB oxidation in vitro using HOCl, and colloidal osmotic pressure was higher than predicted from serum ALB levels in chronic kidney disease patients." (PMID 33804859, 2021). "Albumin levels were a strong predictor of death in several studies in patients with chronic kidney disease." (PMID 34984121, 2021). "Other predictors of decreased serum albumin are age, inflammation, chronic renal disease and general health status." (PMID 32776978, 2020). "All acute and chronic kidney diseases that are characterized by tubular damage are associated with urinary loss of these protein-bound 25(OH)D resulting in a reduction in serum VDBP, albumin, and total-25(OH)D concentration." (PMID 31970483, 2020). "Low platelet counts < 100 × 109/L, serum albumin < 3.5 g/dL, and stage 3–4 chronic kidney disease (eGFR < 60 mL/min/1.73 m2), were present in 18.9, 17.8 and 8.5% of the cohort, respectively." (PMID 32138687, 2020). "The final 9‐variable model included: age, coronary artery disease, blood urea nitrogen, atrial fibrillation, hemoglobin A1c, blood albumin, systolic blood pressure, chronic kidney disease, and smoking history (c = 0.782)." (PMID 31837035, 2020). "For example, all the patients with critical illness had a low albumin, and 10 patients with cardiac failure also had chronic kidney disease." (PMID 33425521, 2020). "Sex, history of chronic kidney disease, hemoglobin concentration, white blood cell counts, serum albumin concentration, the PNI, and RBC transfusion rate differed significantly between the flap failure and flap survival groups." (PMID 32098138, 2020). "Even in chronic kidney disease serum albumin is usually unaffected except in late stages which was also rare in our cohort." (PMID 31936687, 2020). "Approximately 60–80% of zinc is combined with albumin in serum, with an increase in urinary albumin levels, while serum albumin and serum zinc levels decrease in patients with advanced chronic kidney disease." (PMID 33086501, 2020). "Serum albumin is considered a marker of general nutrition and health status in patients with chronic kidney disease." (PMID 32776978, 2020). "We previously reported that inflammation, chronic kidney disease, lower hemoglobin levels, and lower serum albumin levels were independent predictors for ID in HF patients." (PMID 32825781, 2020). "Excess albumin, as occurring in patients with chronic kidney disease (CKD), directly contributes to the development and progression of CKD by inducing tubulointerstitial inflammation and fibrosis in a megalin-dependent manner." (PMID 32172431, 2020).
chronic kidney disease (continued). "Increased excretion of albumin in urine indicates the beginning of evident proteinuria as well as progression to end stage renal disease and cardiovascular disorders." (PMID 31540400, 2019). "Patients with greater age, severe dementia, chronic kidney disease, lower serum albumin, TLC, TC, and hemoglobin levels, as well as higher C-reactive protein levels were more likely to receive TPN." (PMID 31577813, 2019). "Generally, 30 mg/g of ACR is considered the cut-off point of increased urinary excretion of albumin and used to predict chronic kidney disease." (PMID 31590639, 2019). "Urine albumin excretion (random urine ACR) is a marker for kidney damage, and increased ACR is a risk factor for end-stage renal disease (ESRD) and cardiovascular events." (PMID 31308448, 2019). "Serum-creatinine based estimated glomerular filtration rate (eGFRcrea) and urinary albumin-creatinine ratio (UACR) were determined for classification of chronic kidney disease (CKD)." (PMID 30897159, 2019). "In a multivariate analysis, the following variables were associated with mortality (adjusted HR, 95% CI): age 1.04 (1.02–1.05, P < 0.001); chronic kidney disease 1.22 (1.11–1.33, P < 0.001), and plasma albumin 0.96 (0.94–0.99, P < 0.05)." (PMID 30606164, 2019). "In proteinuric nephropathies of chronic kidney disease, the epithelial cells of the nephron including the collecting duct are exposed to high concentrations of luminal albumin." (PMID 31455864, 2019). "The increased UAPN is also a strong independent predictor of diabetic nephropathy progression from macroalbuminuria to end-stage renal disease and is an even better predictor than albumin excretion rate or as good as estimated glomerular filtration rate." (PMID 31269899, 2019). "The presence of small amounts of human serum albumin (HSA) in urine or microalbuminuria (30–300 μg/mL) is a valuable clinical biomarker for the early detection of chronic kidney disease (CKD)." (PMID 31527396, 2019). "While guidelines recommend screening for kidney disease using urinalysis dipstick for patients with hypertension (and urine albumin/creatinine ratio [ACR] for those with diabetes or chronic kidney disease [CKD]), screening remains suboptimal." (PMID 30999886, 2019). "High urinary albumin excretion is a marker of chronic kidney disease (CKD) and a predictor of mortality and cardiovascularevents in the general population and in clinical populations, such as individuals with diabetes." (PMID 31630189, 2019). "Markers of kidney damage were defined as low estimated glomerular filtration rate (eGFR; <60 mL/min per 1·73 m2), presence of albuminuria (urine albumin creatinine ratio >3 mg/mmol); or chronic kidney disease (low eGFR or albuminuria, or both)." (PMID 31708144, 2019). "At baseline, patients in the intervention phase had lower incidence of chronic kidney disease, encephalopathy and upper digestive hemorrhage, lower preoperative levels of creatinine and urea and higher levels of albumin." (PMID 30579327, 2018). "In the German Chronic Kidney Disease cohort, which included 5,217 patients with a mean eGFR of 47.1 ml/min/1.73m2, 41.8% patients had eGFR < 60 ml/min/1.73m2 and urinary albumin/creatinine ratio (ACR) < 30 mg/g." (PMID 29342207, 2018). "There is a growing body of evidence that MR antagonism using Spiro or eplerenone can reduce urinary albumin excretion and retard the progression of chronic kidney disease in several clinical studies." (PMID 29422652, 2018). "Chronic kidney disease (CKD) is defined as glomerular filtration rate (GFR) <60 ml/minute/1.73 m2 or urinary albumin excretion of ≥30 mg/day for more than 3 months." (PMID 30188943, 2018). "We determined differences between estimated glomerular filtration rate (eGFR) using the chronic kidney disease epidemiology collaboration equation and urine albumin to creatinine ratio." (PMID 29682579, 2018).
chronic kidney disease (continued). "Odds ratios for the association between admission serum albumin levels and hospital acquired acute kidney injury (HAKI) occurrence in subgroups of patients with chronic kidney disease (n = 959)." (PMID 29927987, 2018). "The CKD patient’s serum was regarded as the positive control because the proportion of carbamylated albumin has been reported to be high in end-stage renal disease patients." (PMID 28398552, 2017). "In chronic kidney disease, serum albumin was a sensitive marker for the presence of subretinal fluid." (PMID 28819567, 2017). "Specifically, a moderately increased albumin/creatinine ratio often indicates the beginning of chronic kidney disease, and high levels indicate severe kidney disease." (PMID 28422991, 2017). "Chronic Kidney Disease (CKD) refers to kidney damage with manifestations of abnormal excretion of albumin or reduced kidney function, quantified by estimated glomerular filtration rate (eGFR) persisting for greater than three months." (PMID 29610637, 2017). "Recent studies using mass spectrometry demonstrated that albumin cysteinylation in chronic diseases, and in sera of end stage renal disease patients in particular, is greater than in healthy subjects." (PMID 28542419, 2017). "Levels of carbamylated proteins increase significantly in chronic kidney disease and carbamylated albumin is considered as an important biomarker indicating mortality risk." (PMID 28382370, 2017). "The AOPP content of 1 mg/mL of in vitro-generated AOPP-albumin was 7.0 μmol/L and was comparable to the AOPP content of isolated albumin from end stage renal disease patients which ranges from 2 to 10 μmol/L10." (PMID 26905525, 2016). "CYP P450 metabolites of arachidonic acid play an important role in the control of blood pressure, chronic kidney disease through the maintenance of the glomerular permeability barrier to albumin." (PMID 27756246, 2016). "Chronic kidney disease is frequently accompanied by decreased albumin levels, both in adults and in children." (PMID 26885251, 2016). "We provide evidence that AOPP-albumin isolated from end stage renal disease patients as well as in vitro generated AOPPs markedly increase ADP-induced platelet aggregation via CD36." (PMID 26905525, 2016). "This study was planned to compare anti-albumin urea effects of Valsartan alone with combination of Valsartan and Amlodipine in patients of chronic kidney disease with the help of spot UACR." (PMID 27375700, 2016). "Moreover, experimental data show that increased albumin exposure to the tubuli causes tubulo-interstitial damage through activation of pro-inflammatory mediators, which leads to a progressive decline in glomerular and tubular function, ultimately culminating in end-stage renal disease." (PMID 25973922, 2015). "Oral nutritional supplements and other nutritional interventions to chronic kidney disease patients have been suggested to increase serum albumin levels and improve longevity and their quality of life." (PMID 26491522, 2015). "Patients in whom treatment is indicated should be managed to a target of <140/90 mm Hg if aged under 80 years or <130/80 mm Hg in the presence of chronic kidney disease (CKD) if their urinary albumin:creatinine ratio (ACR) is ≥70 mg/mmol." (PMID 26183439, 2015). "It is unconventional, however, to adjust serum Mg for albumin concentrations and only one subject in this study reported having chronic kidney disease." (PMID 25947295, 2015). "The mean albumin of the entire group was less than 40.7g/L reported in 300 end stage renal disease patients in Tehran University of Medical Sciences Hospital during the year 2010." (PMID 26491522, 2015). "Prior investigations have reported advanced age, chronic renal insufficiency, elevated white blood cell count, low serum albumin, use of PPI and H2RB, as well as continued use of systemic antimicrobials to be important risk factors for rCDI." (PMID 24898123, 2014).
chronic kidney disease (continued). "Albumin levels have been found to be inversely correlated with inflammation in end stage renal disease patients." (PMID 24709756, 2014). "After 6 weeks, the rats were sacrificed to determine serum profiles relevant to chronic kidney disease, including albumin, total cholesterol, phosphorus, blood urea nitrogen, and serum creatinine." (PMID 24876873, 2014). "Assessment of albumin and/or protein excretion in the urine is a key step in the early detection and appropriate management of chronic kidney disease (CKD)." (PMID 22958323, 2012). "Several parameters have been recommended for monitoring the nutritional status of children with chronic renal insufficiency, such as serum albumin, height, weight, mid-arm circumference, skin fold thickness, and head circumference." (PMID 23016957, 2012). "In conclusion, our studies have demonstrated that the combination of furosemide and albumin have a superior short-term efficacy over furosemide alone in enhancing water and sodium diuresis in stable hypoalbuminemic chronic kidney disease patients." (PMID 22931630, 2012). "The diagnosis of the patients included liver cirrhosis, malignancy and chronic renal failure which had serum albumin ranging from 1.5 – 3.5 g/dL." (PMID 22931630, 2012). "The glomerular filtration barrier is affected in a large number of acquired and inherited diseases resulting in extensive leakage of plasma albumin and larger proteins, leading to nephrotic syndrome and end-stage renal disease." (PMID 21808734, 2011). "For non-survivors of monobacterial necrotizing fasciitis, the incidences of chronic liver dysfunction, chronic renal failure and thrombocytopenia were higher, and serum albumin values were lower." (PMID 21208438, 2011). "Mean levels of total serum cholesterol, high-density lipoprotein cholesterol, and albumin in patients with end-stage renal disease were lower than those of the general population (160.6 vs. 203.3 mg/dL, 48.5 vs. 59.7 mg/dL, and 3.7 vs. 4.4 g/dL, respectively)." (PMID 15930806, 2005). "Laboratory evaluation showed normocytic normochromic anemia (Hb 11.8 g/dL), chronic kidney disease (eGFR 49 mL/min/1.73 m2), and nephrotic syndrome, with proteinuria (urine protein-to-creatinine ratio: 158 mg/mmol; albumin-to-creatinine ratio: 21 mg/mmol), and low serum albumin (13 g/L)." (PMID 41493762, 2026). "Persistent urinary albumin secretion after delivery may exacerbate renal damage, potentially progressing to chronic kidney disease." (PMID 39857389, 2025). "Chronic kidney disease (CKD), especially when associated with diabetes, greatly increases the chances of having heart problems and dying, and this risk grows with higher levels of albumin in the urine and lower glomerular filtration rate (GFR)." (PMID 40895849, 2025). "Recently, the Prognostic Nutritional Index (PNI), calculated from albumin and lymphocyte levels, has shown potential as a predictor of mortality in various conditions, including cancer, cardiovascular disease, liver disease, and chronic kidney disease." (PMID 40667438, 2025). "The development of integrated predictive models that combine eGFR slope, changes in urinary albumin-to-creatinine ratio (UACR), and promising biomarkers such as TNFRs and KIM-1 holds great potential to enhance the precision of end-stage renal disease (ESRD) risk stratification." (PMID 40469439, 2025). "For instance, oral nutritional supplements specifically designed for kidney diseases can significantly increase serum albumin levels in malnourished patients with chronic kidney disease, reduce the dosage of erythropoietin required, and optimize anthropometric parameters." (PMID 39940308, 2025). "Patients with CKD show persistently decreased estimated glomerular filtration rates (eGFRs) or persistently elevated urine albumin excretion, which may progress to end-stage renal disease." (PMID 39964736, 2025).